MICA (MHC class I polypeptide-related sequence A)
Diseases named in the same sentence as MICA in open-access papers (continued):
Sharing a sentence is not in itself a finding about the gene and the disease.
pancreatic cancer (continued). "In this study, we aimed to detect the effects of high glucose on NK cell-mediated killing on pancreatic cancer cells through reduction of MICA/B expression." (PMID 31088566, 2019). "B, C, MICA/B expression in mRNA and protein levels in the presence of Bmi1 knockdown in both pancreatic cancer cell lines." (PMID 31088566, 2019). "In order to verify the role of GATA2 on MICA/B gene expression, loss-of-function of GATA2 in pancreatic cancer cells was achieved by siRNA knockdown." (PMID 31088566, 2019). "Application of MICA/B antibody significantly blocked the killing effect in both tested pancreatic cancer cell lines." (PMID 31088566, 2019). "We further detected the correlation between Bmi1 and MICA/B in pancreatic cancer tissue using immunohistochemistry." (PMID 31088566, 2019). "In our study, high glucose protects pancreatic cancer from NK cell-mediated killing through suppressing MICA/B expression." (PMID 31088566, 2019). "Bmi1, a polycomb group (PcG) protein, was found to be up-regulated by high glucose, and mediated the inhibition of MICA/B expression through promoting GATA2 in pancreatic cancer." (PMID 31088566, 2019). "Previous findings from our group have shown that the pancreatic carcinoma cell line Panc89 is heterozygous for MICA*009:01 (A6) and MICA*027 (A5), and the prostate carcinoma cell line PC-3 is heterozygous for MICA*008:01:01 (A5.1) and MICA*012:01:01 (A4)." (PMID 30972064, 2019). "Our present study aims at analyzing MICA/B expression in pancreatic tumor tissues and sera, and determining if gemcitabine can stimulate antitumor immunity by inducing MICA/B expression on pancreatic cancer cells." (PMID 21605422, 2011). "Our study has demonstrated that serum MICA levels and MICA/B expression in pancreatic tumor tissues are elevated." (PMID 21605422, 2011). "Seven pancreatic cancer cell lines were analyzed for MICA/B expression by flow cytometry and for their sensitivity to NK-92 cell killing by a 51Cr release assay." (PMID 21605422, 2011). "Statistical analyses revealed that serum MICA levels were significantly increased in pancreatic cancer patients, compared to those in the healthy controls (p = 0.002)." (PMID 21605422, 2011). "MICA/B expression in tumor tissues and sera of pancreatic cancer was analyzed by immunohistochemical staining (IHC) and ELISA, respectively." (PMID 21605422, 2011). "The mean survival of these 16 pancreatic cancer patients with serum MICA levels < 200 pg/ml was 10.3 ± 7.6 months; whereas the mean survival of 45 pancreatic cancer patients with serum MICA levels > 200 pg/ml was 10.3 ± 4.9 months." (PMID 21605422, 2011). "Twenty-five pancreatic cancer specimens from 25 patients (15 male and 10 female) with a mean age of 65 ± 11 (median age: 65, range: 38-81 years) were analyzed for MICA/B expression by immunohistochemical staining according our previous publication." (PMID 21605422, 2011). "The expression level of MICA/B on several pancreatic cancer cells was detected." (PMID 40625735, 2025). "Moreover, we detected the expression of NKG2D ligand MICA/B in pancreatic cancer cells to obtain the optimal target cells." (PMID 36895027, 2023). "Although MICA molecules are not specifically tumor associated antigens, they appear to play a functional role in pancreatic cancer." (PMID 31166958, 2019). "To further explore whether the decreased killing of NK cells was related with the changes of MICA/B expression in pancreatic cancer cells, we performed anti-MICA/B blocking experiments with specific antibody against MICA/B." (PMID 31088566, 2019). "Moreover, after AMPK signaling was activated under high glucose, Bmi1 decreased, GATA2 increased and MICA/B recovered in pancreatic cancer cells." (PMID 31088566, 2019). "Moreover, Bmi1 inhibits MICA/B expression through up-regulating of GATA2 in pancreatic cancer cells, contributing to the immune escape eventually." (PMID 31088566, 2019).
pancreatic cancer (continued). "Pancreatic tumor cells may avoid immune surveillance by releasing the transmembrane major histocompatibility complex class I chain-related A (MICA) protein in soluble form (s-MICA)." (PMID 31166958, 2019). "In this process, constitutive activation of AMPK-Bmi1-GATA2 axis could mediate MICA/B inhibition, which may serve as a therapeutic target for further intervention of pancreatic cancer immune evasion." (PMID 31088566, 2019). "In this study, we develop our hypothesis that high glucose affects the expression of Bmi1, AMPK, GATA2, and MICA/B and promotes pancreatic cancer cells to escape from immune surveillance." (PMID 31088566, 2019). "This inhibition was related to the reduced MICA/B expression on pancreatic cancer cells." (PMID 31088566, 2019). "In addition, in an exploratory analysis, we investigated the pancreatic cancer risk associated with four other MICA-STR polymorphisms and eight MICA single nucleotide polymorphisms (SNPs) with known associations to cancer." (PMID 31166958, 2019). "In pancreatic cancer, the low expression of MICA was considered to be related to poor prognosis." (PMID 24885711, 2014). "The levels of MICA/B expression in serum and tissue of pancreatic cancer are elevated." (PMID 21605422, 2011). "In this study, we sought to study MICA/B expression in pancreatic cancer and to determine whether and how genotoxic drugs such as gemcitabine can affect MICA/B expression and natural killer cytotoxity." (PMID 21605422, 2011). "Since soluble MICA/B can antagonize membrane-bound MICA/B-mediated antitumor immunity, the impact of genotoxic drug- or radiation-induced MICA/B expression in pancreatic tumor cells in a clinical setting remains unknown." (PMID 21605422, 2011). "Our study confirms the expression of MICA/B in pancreatic adenocarcinomas, showing that 17 of 25 pancreatic adenocarcinomas (68%) were positive for MICA/B expression; and that MICA/B expression was detected in 4 of 7 pancreatic cancer cell lines." (PMID 21605422, 2011). "MICA/B expression was analyzed in 7 pancreatic cancer cell lines by flow cytometry." (PMID 21605422, 2011). "The resistance of MICA/B-positive pancreatic cancer to NK-92 cell killing could be due to the inhibitory effect of co-expressed HLA-G antigen that suppresses NK cell function." (PMID 21605422, 2011). "However, no epidemiologic studies to date have evaluated the MICA A5.1 polymorphism in relation to pancreatic cancer risk." (PMID 31166958, 2019). "Therefore, MICA/B expression in pancreatic cancer and subsequent release as soluble molecules may have a very intriguing impact in clinical outcome." (PMID 21605422, 2011). "The molecular mechanisms of increased MICA/B expression in pancreatic cancer are unknown." (PMID 21605422, 2011). "This is consistent with previous findings that low concentrations of gemcitabine increase the expression of MICA/B, the NKG2D ligand, in pancreatic cancer cell lines and elicit a potent apoptotic effect in NK cells." (PMID 37169953, 2023). "We further verified that high glucose can promote the GATA2 to bind to the MICA and MICB promoter in pancreatic cancer under high glucose environment using ChIP assay." (PMID 31088566, 2019). "In particular, valproic acid (VPA) has been reported to upregulate MICA/B with a mechanism dependent on PI3K/Akt pathway in pancreatic cancer cells, while the involvement of ERK in MICA/B and ULBP2 upregulation in response to VPA has been shown in MM cells." (PMID 28993779, 2017). "The expression of MICA and MICB in pancreatic cancer was significantly correlated with late TNM stage, tumor differentiation and lymphatic invasion." (PMID 24885711, 2014). "To explore the mechanism by which VPA upregulates MICA and MICB in pancreatic cancer cells, we examined the expression and activation of components of the HER2/HER3, ATM/ATR, and PI3K/Akt pathways." (PMID 24885711, 2014).
pancreatic cancer (continued). "Our results demonstrate that VPA enhances the susceptibility of pancreatic cancer cells to NK cell-mediated lysis by upregulating the expression of MICA and MICB on pancreatic cancer cells." (PMID 24885711, 2014). "Levels of MICA/B are also elevated in pancreatic cancer and the inhibition of MICA/B, mediated by constitutive activation of the AMPK-GATA2 axis, may serve as a therapeutic target of pancreatic cancer immune evasion." (PMID 36009530, 2022). "In our analysis of additional MICA STR polymorphisms, we did not observe any significant association between the A4, A5, A6, or A9 MICA STR polymorphisms and pancreatic cancer risk." (PMID 31166958, 2019). "The release of MICA into circulation may lead to decreased binding affinity between NKG2D-bearing immune cells and pancreatic tumor cells, resulting in insufficient immune surveillance." (PMID 31166958, 2019). "Moreover, we provide evidence to confirm that the VPA-induced upregulation of MICA and MICB in pancreatic cancer cells is dependent on the PI3K/Akt signaling pathway." (PMID 24885711, 2014). "However, the present study demonstrated that inactivation of PI3K using LY294002 or a siRNA attenuated the ability of VPA to upregulate the expression of MICA and MICB in pancreatic cancer cells." (PMID 24885711, 2014). "The NKG2DLs MICA and MICB play an important role in the NK cell-mediated lysis of cancer cells; therefore, we determined the effect of VPA on the expression of MICA and MICB mRNA in the human pancreatic cancer cell lines PANC-1, MIA PaCa-2, and BxPC-3." (PMID 24885711, 2014). "In order to explore whether VPA has potential as a treatment for pancreatic cancer, we examined the effects and mechanism of VPA action on the expression of MICA and MICB in human pancreatic cancer cells." (PMID 24885711, 2014). "Immunohistochemistry analysis revealed the MICA and MICB expression in pancreatic cancer." (PMID 24885711, 2014). "Therefore, we analyzed the effect of VPA on the expression of MICA and MICB in pancreatic cancer cell lines." (PMID 24885711, 2014). "Although the role of PI3KCA siRNA on the expression of MICA and MICB protein was not totally compatible with its role on the NK cell-mediated lysis, the trend suggested that PI3K/Akt pathway played an important role in VPA-induced upregulation of MICA and MICB in pancreatic cancer cells." (PMID 24885711, 2014). "Serum MICA/B levels were significantly elevated in patients with pancreatic adenocarcinomas but did not correlate with the stage of pancreatic cancer and patient survival." (PMID 21605422, 2011). "Thus, out of six different epigenetic modifiers tested, only HDAC inhibitor VPA increased cell surface expression and/or release of MICA, MICB and ULBP-2 from the pancreatic carcinoma and prostate carcinoma cell lines irrespective of their allelic MICA variation." (PMID 30972064, 2019). "In fact, NKG2D ligand (MICA/B and ULBP-2) gene expression was remarkably induced with 2.5 mM VPA both on malignant (pancreatic carcinoma cells Panc89 and prostate carcinoma cells PC-3) and non-malignant cells (PBMC and γδ T cells)." (PMID 30972064, 2019). "We also examined the surface expression of MICA and MICB in pancreatic cancer cells treated with or without 1 mM VPA for 24 h." (PMID 24885711, 2014). "MICA/B expression was detected in a positive control cell line (MRO87) and in 4 pancreatic cancer cell lines (PANC-1, MPANC96, HPAF-II, and CAPAN-1) but not in the other 3 cell lines (COLO-587, MiaPaCa, and CAPAN-2)." (PMID 21605422, 2011).
acute myeloid leukemia (21 papers, 2014 to 2026). Acute myeloid leukemia (AML) is a group of neoplasms arising from precursor cells committed to the myeloid cell-line differentiation. "The KLF4 transcription factor also has been linked to the expression of MICA in acute myeloid leukaemia (AML)." (PMID 37626965, 2023). "In another study, stem cells from acute myeloid leukemia (AML) showed low expression of the ligands of NKG2D MICA/B and ULBPs." (PMID 33918136, 2021). "Indeed, in acute myeloid leukemia cells, the shedding of MICA/B was significantly inhibited by increased expression of TIMP338." (PMID 32968163, 2020). "In patients with chronic lymphocytic leukemia (CLL), acute myeloid leukemia (AML), and multiple myeloma, NK cells show reduced expression of NKG2D, which in turn is linked to enhanced levels of MICA and MICB, thereby causing anergy in NK cells." (PMID 38239881, 2023). "In the presented study, we investigated the single amino acid changes across the exons 2–4 of MICA and MICB genes, and point mutations within the NKG2D gene, which defines the type of NKG2D haploblock (HNK/LNK) in the donors (n = 124), as well as in patients with acute myeloid leukemia (n = 78)." (PMID 34682758, 2021). "Acute myeloid leukemia (AML) often evades this surveillance by downregulating NKG2D ligands (NKG2D‐L), especially MICA." (PMID 41532367, 2026). "Sodium valproate, a low affinity pan HDACi, can induce the expression of NKG2D ligands MICA, ULBP2, and ULBP3 in tumor cells, including primary patient acute myeloid leukemia (AML) cells, resulting in enhanced CD107a degranulation of NK cells." (PMID 38665224, 2024). "In particular, HDACi upregulated NKG2D-L, such as MICA/B and ULBP1, on multiple tumor cell lines, both from hematological and solid tumors and on patient-derived acute myeloid leukemia (AML) cells, leading to increased sensitivity to NK cell-mediated cytotoxicity." (PMID 33572396, 2021). "This applies in particular to acute myeloid leukemia (AML), which evades immune detection by downregulation of NKG2D ligands (NKG2D-L), including MICA." (PMID 37143070, 2023). "Shedding of NKG2D ligands, including MICA, MICB and ULBP2, is inhibited by TIMP-3 in acute myeloid leukemia (AML) cells, and this process enhances their sensitivity to lytic activity of NK." (PMID 35207132, 2022). "In addition, elevated DNA-“hyper”-methylations for NKG2DLs could be detected in some malignant cells, mainly in acute myeloid leukemia (AML) cells, resulted in a clearance of NKG2DL surface cell expression, also detected for MICA, ULBP1/2 in AML patients." (PMID 28943878, 2017).
ovarian carcinoma (21 papers, 2009 to 2025). A malignant neoplasm originating from the surface ovarian epithelium. "NKG2DLs are upregulated in various cancers: MICA in breast, lung, and ovarian cancers, ULBP1–5 in breast cancer, and ULBP6/2/5 in lung cancer." (PMID 40116579, 2025). "Although MICA/B levels are generally higher in ovarian cancer tissues compared to normal ovarian epithelium, their expression does not appear to change significantly in relapsed patients." (PMID 40919157, 2025). "Elevated expression of miR-20a in tumor tissues of advanced-stage ovarian cancer patients has been shown to reduce the cytotoxic activity of natural killer (NK) cells by downregulating MICA/B expression." (PMID 40919157, 2025). "Soluble MICA for ovarian cancer cells, while induced by platelet cloaking, saw only modest increases in levels in the microenvironment and is therefore unsurprising that neutralising sMICA in the releasate has no measurable effect." (PMID 30908480, 2019). "This has been observed in ovarian cancer, where high expression of MICA/B significantly correlated with lower degree of NK cells intra-epithelial infiltration." (PMID 29221214, 2017). "Additionally, other well-characterized NKG2DLs, such as MICA/B was also found to be epigenetically silenced in liver, and ovarian cancer." (PMID 40551137, 2025). "Interestingly, Huang and coworkers have shown that combination of valproate, known to upregulate cell surface MICA/B, and metalloproteinase inhibitors was found to significantly stabilize cell surface MICA/B on ovarian carcinoma cells and to enhance in vivo the efficacy of immune cell therapy." (PMID 26161387, 2015). "In hematological malignancies and solid tumors, MICA or MICB is expressed in 100% of colorectal tumors, 97% of breast cancers, 95% of renal cell carcinomas, 81% of ovarian cancer, 77% of primary cutaneous melanomas, and 50% of primary uveal melanomas." (PMID 40612946, 2025). "Various NKG2DLs, such as MICA/B and ULBP-1, -2, -3, and -4, are expressed across established ovarian cancer cell lines and primary ovarian cancer samples." (PMID 40612946, 2025). "NKG2D CAR-T cells recognize stress ligands (MICA/B, ULBP1–6) expressed on over 80% of diverse solid tumors, including pancreatic and ovarian cancers, thereby broadening therapeutic applicability." (PMID 41007874, 2025). "Significantly reduced expression of NKG2D, high level of MICA as well as IL-6, IL10 and TNF-α indicates immune suppression of ovarian cancer patients.." (PMID 37322531, 2023). "A separate study on ovarian cancer reported that patients had reduced numbers of NKG2D-expressing CD56 bright NK cells, while soluble MICA levels were elevated." (PMID 37626965, 2023). "Early studies have shown that the expression rate of MICA/B and ULBP1-4 is 60–88% in ovarian cancer tissues, while expression of MICA/B and ULBP2-4 is more common in ovarian cancer cell lines." (PMID 28426690, 2017). "To assess the cytotoxic activity of CD8+ CIK cells on ovarian cancer cells, we screened a panel of ovarian cancer cell lines for the expression of NKG2D ligands including MICA, MICB and ULBP1-4 by qPCR." (PMID 28426690, 2017). "The poor prognostic significance of ULBP2 expression in ovarian cancer was confirmed in a second independent study in which MICA/B lacked prognostic significance." (PMID 37626965, 2023). "McGilvray and colleagues corroborated the poor prognosis in ovarian cancer using a larger cohort of patients where expression of high levels of ULBP-1-5 correlated with decreased survival, whereas MICA expression did not correlate with disease progression." (PMID 30150983, 2018).